SRR (serine racemase)
Description:
Pyridoxal-5'-phosphate (PLP)-dependent enzyme that catalyzes the synthesis of D-serine from L-serine. D-serine is a key coagonist with glutamate at NMDA receptors. In addition to racemization, has dehydratase activity towards both L-serine and D-serine, a two-step reaction in which the hydroxyl group of serine is eliminated to produce aminoacrylate (2-aminoprop-2-enoate), and then the aminoacrylate (an unstable intermediate) is deaminated by nonenzymatic hydrolysis to produce pyruvate (By similarity).
Synonyms: ILV1; ISO1
Tractability: Small molecule: a structure with a bound ligand is known; a high-quality ligand is known; it has a binding pocket of medium quality. PROTAC: ubiquitination databases record sites on it; its protein half-life has been measured.
Target class: Enzyme
Gene: Protein-coding gene on chromosome 17 (2,303,383 to 2,325,260, forward strand). Ensembl gene ENSG00000167720.
Subcellular location (Human Protein Atlas): Vesicles
Pathways (Reactome):
Metabolism: Serine metabolism
Gene Ontology:
Molecular function: ATP binding; identical protein binding; L-serine ammonia-lyase activity; magnesium ion binding; PDZ domain binding; protein binding; protein homodimerization activity; pyridoxal phosphate binding; serine racemase activity; calcium ion binding; D-serine ammonia-lyase activity; glycine binding; threonine racemase activity; metal ion binding
Biological process: D-serine biosynthetic process; L-serine metabolic process; pyruvate biosynthetic process; response to lipopolysaccharide; amino acid metabolic process; response to ketamine; response to xenobiotic stimulus
Cellular component: cytoplasm; neuronal cell body; cytosol; apical part of cell
Genetic constraint (gnomAD): Loss-of-function variants: 19 observed, 32.25 expected, observed/expected ratio (o/e) 0.59, 90% interval 0.41 to 0.86. The upper end of that interval is the gene's LOEUF score, 0.86, which puts it in group 3 of 6, group 1 being the genes least tolerant of losing a copy. Missense variants: 358 observed, 411.92 expected, observed/expected ratio (o/e) 0.87, 90% interval 0.8 to 0.95. Synonymous variants: 138 observed, 145.79 expected, observed/expected ratio (o/e) 0.95, 90% interval 0.82 to 1.09.
Homologues: Orthologues: chimpanzee SRR (99% identical), macaque SRR (97% identical), mouse Srr (90% identical), rat Srr (89% identical), pig SRR (86% identical), guinea pig SRR (80% identical), tropical clawed frog srr (64% identical), Caenorhabditis elegans serr-1 (35% identical). Paralogues in human: CBS (27% identical), SDSL (21% identical), SDS (19% identical), THNSL1 (16% identical), THNSL2 (15% identical).
Diseases named in the same sentence as SRR in open-access papers:
SRR is named in the same sentence as 43 diseases in open-access papers, as found by Europe PMC text mining. Sharing a sentence is not in itself a finding about the gene and the disease. The quoted sentences say what the papers report.
schizophrenia (31 papers, 2007 to 2026). A major psychotic disorder characterized by abnormalities in the perception or expression of reality. "Abnormality in l-serine, which is converted to d-serine by the schizophrenia-associated gene serine racemase, has also been reported, but results across studies are less consistent." (PMID 38694089, 2024). "Of interest, Disrupted-In-Schizophrenia-1 (DISC-1), which has been repeatedly associated with schizophrenia, has been found to bind to and stabilize serine racemase." (PMID 35883465, 2022). "As indicated in a recent review, decreased serine racemase expression and the genetic depletion of serine racemase are linked to cognitive disorders such as schizophrenia and addiction." (PMID 31547425, 2019). "The factors regulating D-serine are important for understanding normal NMDA receptor function and because D-serine, along with DAO and SRR, is implicated in the pathogenesis and treatment of schizophrenia." (PMID 20091774, 2010). "Moreover, evidence of abnormalities in the D-serine pathway highlights its critical role in schizophrenia pathogenesis: these include risk gene encoding the enzymes SRR and DAAO, altered levels of D-serine, L-serine, glycine as well as SHMT1." (PMID 38849515, 2024). "In humans, genetic variation of the serine racemase gene is associated with schizophrenia." (PMID 37238689, 2023). "SRR encodes for an enzyme that converts L- to D-serine, which has be found to be lower in the CSF of patients with schizophrenia, supporting the role of glutamatergic neurotransmission in the biology of schizophrenia and affective disorders." (PMID 30142156, 2018). "Therefore, a deleted or decreased Serine-racemase expression may also be associated with cognitive disorders such as schizophrenia, indicating that D-Serine is intensely linked to memory and/or learning developments." (PMID 35225861, 2022). "Consequently, DAO and serine racemase might be key enzymes for the association between D-amino acids and schizophrenia." (PMID 35225861, 2022). "Exploratory studies of functional abnormalities in genetic animal models with the knockout of serine racemase (SR-KO) have contributed to the acquisition of numerous findings about the pathophysiology and pathomechanisms of schizophrenia." (PMID 39334894, 2024). "Knockout mice for serine racemase are also used as an established model of schizophrenia because they satisfactorily mimic NMDA receptor hypofunction." (PMID 36451159, 2022). "For instance, protein interacting with C kinase (PICK1), a protein required for serine racemase functioning, has been found to be altered in “disorganized” schizophrenia, as reported in a case–control study enrolling Japanese subjects." (PMID 35883465, 2022). "Genome-wide association studies have identified genetic variants related to the structure and function of the NMDAR that are associated with schizophrenia, including GRIN2A and serine racemase (SRR)." (PMID 34385418, 2021). "These genes have been investigated as a potential therapeutic target in schizophrenia such as the SRR gene which codes for Serine Racemase." (PMID 34502372, 2021). "Large-scale genome-wide association studies (GWAS) have identified a set of common genetic variants in glutamatergic genes in patients with schizophrenia, including, for instance, GRM3, GRIN2A, GRIA1, SRR, CLCN3, among others." (PMID 31431615, 2019). "The present work investigated social interactions in mice when NMDA receptor transmission is disrupted indirectly and in a manner likely relevant to the etiology of schizophrenia, through deletion of the serine racemase gene." (PMID 31515952, 2019). "Many genes associated with glutamateric neurotransmission have been previously implicated in schizophrenia, including GRM3, GRIN2A, SRR and GRIA1." (PMID 29181591, 2017). "Human genetic studies and expression studies have associated PDE4B, FEZ1, SRR, and KALRN with schizophrenia." (PMID 25762938, 2015).
schizophrenia (continued). "Fine-mapping/exome sequencing also identified coding variants associated with substantial risks for schizophrenia in the NMDAR (GluN2A), the AMPAR (GluA3), the KAR (GluK2 and GluK4), and PSD-95-associated genes (SHANK, NLGN, and DLGAP) and serine racemase (SR)." (PMID 39334894, 2024). "The reduced activity of D-serine at NMDA receptors may be central to the aetiology of schizophrenia, and, in agreement with this theory, the reduction of serine racemase activity produces schizophrenia-like phenotypes in animal models." (PMID 37238689, 2023). "In the context of the NMDA receptor hypofunction hypothesis, the SRR agonist may serve as a therapeutic target for schizophrenia." (PMID 37259423, 2023). "Postmortem brain studies have also indicated decreased expression of the NR1 subunit (mRNA and protein) and NR2C subunit (mRNA) in the postmortem dorsolateral prefrontal cortex in schizophrenic patients and reductions in D-serine and serine racemase (SR) levels in patients with schizophrenia." (PMID 34658976, 2021). "Given the role of D-serine in both neurodevelopment and the pathophysiology of schizophrenia, we examined whether neonatal disruption of D-serine synthesis by SRR inhibition could induce behavioral abnormalities relevant to schizophrenia, in later life." (PMID 23630632, 2013). "We studied d-amino acid oxidase and serine racemase immunohistochemically in several brain regions and compared their immunoreactivity and their mRNA levels in the cerebellum and dorsolateral prefrontal cortex in schizophrenia." (PMID 17880399, 2007). "However, the observation of reduced ASCT1 expression in schizophrenia suggests that increasing serine racemase activity or ASCT1 expression may be beneficial in this condition." (PMID 37238689, 2023). "Another field of application of the SRR agonist could be schizophrenia." (PMID 37259423, 2023). "Additionally, the SRR-knockout mouse model recapitulates reduction in NMDAR function and most of the phenotypic characteristics of schizophrenia, including structural pathology, EEG abnormalities and impaired cognition." (PMID 38849515, 2024). "Serine racemase knockout mice demonstrate abnormalities in socio‐communicative behaviors consistent with an impairment in sociality, a negative symptom of schizophrenia." (PMID 31515952, 2019). "The association of serine racemase, synthesizing serine enzyme, with schizophrenia was found, as well as mice with a lack of serine racemase gene showed behavior similar to schizophrenia." (PMID 32116664, 2019). "Yet, socio‐communicative deficits, a characteristic of schizophrenia, have not been reported in serine racemase knockout mice." (PMID 31515952, 2019). "SRR immunoreactivity was increased in schizophrenia, but unlike DAO, this occurred in the DPFC not the cerebellum, and was not accompanied by elevated SRR mRNA." (PMID 17880399, 2007). "Serine racemase was increased in schizophrenia in the dorsolateral prefrontal cortex but not in cerebellum, while serine racemase mRNA was unchanged in both regions." (PMID 17880399, 2007). "Overall, therefore, no consensus has yet emerged from the data regarding SRR expression, nor d-serine itself, in the cerebral cortex in schizophrenia." (PMID 17880399, 2007). "Furthermore, both reduced brain serine racemase (SRR) and increased DAO protein levels may contribute to a decrease in CSF D-serine levels in schizophrenia." (PMID 34575878, 2021).
type 2 diabetes (7 papers, 2010 to 2024). "We previously showed that both human and mouse pancreatic islets express the D-serine synthetic enzyme serine racemase (Srr), for which genetic polymorphisms have been correlated to gestational diabetes, type II diabetes, and the therapeutic efficacy of the antidiabetic drug metformin." (PMID 33430405, 2021). "In another study, it has been observed that the serine racemase (SRR) gene is involved in type 2 diabetes." (PMID 35046895, 2021). "SRR rs391300 was originally identified as genetic determinants of type 2 diabetes by GWA studies on Han Chinese in 2009." (PMID 22096510, 2011). "Increased expression of SRR has been observed in type 2 diabetes mellitus similar to results in the GTEx portal database showing that the expression of rs391300 where T is the risk allele (TT and TC genotypes) has an increased expression ratio when compared to the CC genotype." (PMID 39561140, 2024). "The study identified PTPRD and Serine Racemase (SRR) as novel type 2 diabetes susceptibility genes not observed in Japanese and Western population." (PMID 20625434, 2010).
Alzheimer disease (5 papers, 2017 to 2023). A progressive, neurodegenerative disease characterized by loss of function and death of nerve cells in several areas of the brain leading to loss of cognitive function such as memory and language. "As a proof of concept, the SRR agonist NSC294149 was applied to the Alzheimer’s disease (AD) fruit fly model (Drosophila melanogaster)." (PMID 37259423, 2023). "Similarly, in Alzheimer’s disease, astrocytes become reactive and neurotoxic, upregulate serine racemase, and release D-serine." (PMID 37238689, 2023).
type 2 diabetes mellitus (5 papers, 2010 to 2024). A type of diabetes mellitus that is characterized by insulin resistance or desensitization and increased blood glucose levels. "In conclusion, we found the retinal neurodegeneration and microvascular damage induced by diabetes was significantly attenuated in SRR-KO mice." (PMID 29304076, 2018). "Six months after the onset of diabetes, in the posterior retinas, we found that the number of RGCs expressing Brn3 was significantly lower in diabetic WT and SRR-KO mice than those of control mice." (PMID 29304076, 2018). "Further studies will need to clarify the mechanisms that SRR plays a role in retinal microvascular damage in diabetes." (PMID 29304076, 2018). "Our results showed the attenuation of degeneration of retinal neuronal cells and microvascular damage induced by diabetes in SRR-KO retinas." (PMID 29304076, 2018). "Six months after the onset of diabetes, the number of survived retinal ganglion cells was higher in SRR-KO mice than that of WT mice." (PMID 29304076, 2018). "To evaluate the microvascular damage in diabetic WT and SRR-KO mice six months after the onset of diabetes, we counted the number of acellular capillaries." (PMID 29304076, 2018). "Six months after the onset of diabetes, we found that the number of RGCs was higher and the number of acellular capillaries was lower in SRR-KO mice than those of WT mice." (PMID 29304076, 2018). "We characterized STZ-induced DR of WT and SRR-KO mice 6 months after the onset of diabetes." (PMID 29304076, 2018). "In this study, we examined the expression of SRR in mouse retina, and compared the degeneration of retinal neuronal cells and retinal microvascular damage between diabetic wild type (WT) and SRR-KO mice in long-term diabetes." (PMID 29304076, 2018). "As the expression of SRR is enhanced by inflammatory stimuli in vivo, increased expression of SRR might be a result from inflammation occurring in diabetes." (PMID 29304076, 2018). "Thus, the suppression of SRR activity may have protective effects on the retinal neurons and vasculature in diabetes." (PMID 29304076, 2018). "We studied Chinese patients with T2D and identified two genes, PTPRD and SRR, that were not previously known to be involved in diabetes and are involved in biological pathways different from those implicated in T2D by previous association reports." (PMID 20174558, 2010).
cognitive deficits (3 papers, 2019 to 2021). "In the degenerating population, rs391300 polymorphism of the Serine Racemase (SRR) gene was associated with T2D and the progression of mild cognitive impairment (MCI) to AD." (PMID 33352859, 2020).
colorectal cancer (3 papers, 2021 to 2025). A primary or metastatic malignant neoplasm that affects the colon or rectum. "Serine racemase (SRR) supports proliferation of colorectal cancer cells by the dehydration of l-serine and d-serine, resulting in the formation of pyruvate and ammonia." (PMID 36232473, 2022). "Inhibition of SRR suppresses the proliferation of colorectal cancer cells and augments the efficacy of the conventional chemotherapeutic reagent 5-FU in vivo." (PMID 33401771, 2021). "Notably, serine racemase inhibition was found to suppress colorectal cancer cell proliferation and enhance the efficacy of 5‐FU in vivo, implying that targeting serine racemase could be a promising therapeutic strategy." (PMID 40552664, 2025). "SRR expression is upregulated in colorectal adenoma and adenocarcinoma lesions when compared with non-neoplastic mucosa in human colorectal cancer samples." (PMID 33401771, 2021).
osteosarcoma (3 papers, 2016 to 2025). A usually aggressive malignant bone-forming mesenchymal neoplasm, predominantly affecting adolescents and young adults. "miR-193a-5p inhibits TGF-β, Myc/Max, and ATF2/ATF3/ATF4 signaling pathways, thereby regulating the expression of serine racemase (SRR) and inhibiting the migration and invasion of osteosarcoma." (PMID 40161373, 2025). "Our present study showed for the first time that miR-193a-3p and miR-193a-5p can suppress human osteosarcoma cell metastasis by suppressing two novel targets, Rab27B and SRR, respectively." (PMID 26913720, 2016). "Our work suggested for the first time that miR-193a-3p-regulated Rab27B and miR-193a-5p-regulated SRR contribute to the invasion and metastasis of osteosarcoma." (PMID 26913720, 2016). "To clarify the biological roles of Rab27B and SRR in osteosarcoma cells, we knocked down endogenous Rab27B and SRR expression using specific small interfering RNAs (siRNAs) in MG63.2 cells." (PMID 26913720, 2016). "Taken together, these results suggested that Rab27B and SRR are direct and functional targets of miR-193a-3p and miR-193a-5p, respectively, and that they are involved in the miRNA-induced suppression of osteosarcoma cell migration and invasion." (PMID 26913720, 2016). "In this study, we demonstrated that miR-193a-3p and miR-193a-5p suppress the metastasis of human osteosarcoma cells by repressing Rab27B and SRR expression, through suppressing the TGFβ, Myc/Max and ATF2/ATF3/ATF4 signaling pathways." (PMID 26913720, 2016). "Here, we revealed for the first time that miR-193a-3p and miR-193a-5p are also involved in the suppression of osteosarcoma metastasis through two newly identified target genes, namely Rab27B and SRR." (PMID 26913720, 2016). "We next determined if Rab27B and SRR dysregulation was involved in the miR-193a-3p- and miR-193a-5p-induced migration and invasion of osteosarcoma cells." (PMID 26913720, 2016). "Hence, miR-193a-3p and miR-193a-5p negatively regulate osteosarcoma metastasis by targeting Rab27B and SRR, respectively." (PMID 26913720, 2016). "MiR-193a-3p and miR-193a-5p play important roles in osteosarcoma metastasis through down-regulation of the Rab27B and SRR genes and therefore may serve as useful biomarkers for the diagnosis of osteosarcoma and as potential candidates for the treatment of metastatic osteosarcoma." (PMID 26913720, 2016).
Insulin resistance (2 papers, 2014 to 2021). Increased resistance towards insulin, that is, diminished effectiveness of insulin in reducing blood glucose levels. "Collectively, we found that the genes SRR, PDE4B, and NFKB1A were directly and indirectly associated with insulin secretion, insulin resistance, and T2DM." (PMID 35046895, 2021).
memory impairment (2 papers, 2022 to 2023). "Administration of d-serine has shown promising results in rescuing learning and memory impairments induced by SRR knockout and environmental factors in flies and rodents." (PMID 37833512, 2023).
Stroke (2 papers, 2020 to 2025). Sudden impairment of blood flow to a part of the brain due to occlusion or rupture of an artery to the brain. "More clinical trials are warranted to translate promising approaches from animal studies to human clinical trials, e.g., serine racemase inhibition, or to investigate agents that have been studied with regard to endothelial dysfunction but not in the context of stroke, e.g., SSRIs." (PMID 39812851, 2025).
brain injury (1 paper, 2023). Acute and chronic (see also brain INJURIES, CHRONIC) injuries to the brain, including the cerebral hemispheres, CEREBELLUM, and brain STEM. "For example, in traumatic brain injury, astrocytes become reactive and upregulate serine racemase, causing an increase in the cytoplasmic D-serine concentration." (PMID 37238689, 2023).
Cerebral ischemia (1 paper, 2022). Restriction of arterial blood supply to the brain associated with insufficient oxygenation to support the metabolic requirements of the tissue. "Immunostaining showed that the expression of SRR was enhanced in the neurons on the ischemic side, suggesting that neurons are the source of DS during cerebral ischemia." (PMID 35269435, 2022). "As an in vivo model of cerebral ischemia in mice, an embolization thread made of nylon thread was inserted into the internal carotid artery of wild-type (WT) and SRR-/- mice, until the origin of the middle cerebral artery (MCA) and the MCA was occluded." (PMID 35269435, 2022).